MEIS3 (Meis homeobox 3)
Description:
Transcriptional regulator which directly modulates PDPK1 expression, thus promoting survival of pancreatic beta-cells. Also regulates expression of NDFIP1, BNIP3, and CCNG1.
Synonyms: MRG2; DKFZp547H236
Tractability: No criterion of Open Targets' tractability assessment is met for any kind of drug.
Gene: Protein-coding gene on chromosome 19 (47,403,124 to 47,419,530, reverse strand). Ensembl gene ENSG00000105419.
Subcellular location: Nucleus
Subcellular location (Human Protein Atlas): Nucleoplasm
Gene Ontology:
Molecular function: sequence-specific DNA binding; sequence-specific double-stranded DNA binding; DNA-binding transcription activator activity, RNA polymerase II-specific; DNA-binding transcription factor activity, RNA polymerase II-specific; RNA polymerase II cis-regulatory region sequence-specific DNA binding; DNA binding
Biological process: angiogenesis; animal organ morphogenesis; brain development; embryonic pattern specification; eye development; hemopoiesis; positive regulation of cell population proliferation; positive regulation of transcription by RNA polymerase II; regulation of DNA-templated transcription
Cellular component: chromatin; nucleus
Genetic constraint (gnomAD): Loss-of-function variants: 38 observed, 45.95 expected, observed/expected ratio (o/e) 0.83, 90% interval 0.64 to 1.08. The upper end of that interval is the gene's LOEUF score, 1.08, which puts it in group 4 of 6, group 1 being the genes least tolerant of losing a copy. Missense variants: 456 observed, 486.73 expected, observed/expected ratio (o/e) 0.94, 90% interval 0.87 to 1.01. Synonymous variants: 198 observed, 191.87 expected, observed/expected ratio (o/e) 1.03, 90% interval 0.92 to 1.16.
Homologues: Orthologues: macaque MEIS3 (98% identical), chimpanzee MEIS3 (98% identical), guinea pig MEIS3 (91% identical), rat Meis3 (91% identical), dog MEIS3 (90% identical), mouse Meis3 (90% identical), rabbit MEIS3 (85% identical), tropical clawed frog meis3 (75% identical), zebrafish meis3 (65% identical), Drosophila melanogaster hth (57% identical), Caenorhabditis elegans unc-62 (45% identical), Drosophila melanogaster exd (20% identical), and 4 more. Paralogues in human: MEIS3P2 (90% identical), MEIS2 (70% identical), MEIS1 (67% identical), PKNOX2 (39% identical), PKNOX1 (37% identical), PBX1 (23% identical), PBX2 (22% identical), PBX3 (22% identical), PBX4 (21% identical), TGIF1 (16% identical), TGIF2 (13% identical), TGIF2LX (11% identical), and 1 more.
Diseases named in the same sentence as MEIS3 in open-access papers:
MEIS3 is named in the same sentence as 28 diseases in open-access papers, as found by Europe PMC text mining. Sharing a sentence is not in itself a finding about the gene and the disease. The quoted sentences say what the papers report.
cognitive decline (2 papers, 2023 to 2024). "As the most significant mRNA biomarker of AD identified via TEMINET, MEIS3 was revealed through differential expression analysis to be considerably linked with cognitive decline and increased neurofibrillary tangle density." (PMID 38338932, 2024). "Notably, for example, gene MEIS3 (P-value = 1.16 × 10–8 for cognitive decline) and gene NPNT (p-value = 1.49 × 10–6 for tangle density) have previously identified as differentially expressed genes in the context of AD in earlier studies." (PMID 37789141, 2023).
gastric cancer (2 papers, 2019 to 2025). A primary or metastatic malignant neoplasm involving the stomach. "In this study, we systematically delineated the transcriptional regulatory landscape of THY1 in gastric cancer by identifying six robust putative regulators—PRRX1, TWIST1, SNAI2, MEIS3, VENTX, and EGR2—through an integrative multicohort approach." (PMID 40476057, 2025).
ovarian carcinoma (2 papers, 2019 to 2020). A malignant neoplasm originating from the surface ovarian epithelium. "In addition, MEIS3, a member of the MEIS family involved in vertebrate tumorigenesis, has been detected to be expressed at a low level in ovarian carcinoma cells, hereby validating its functionality in regulating malignant cell survival." (PMID 33520978, 2020).
Alzheimer disease (1 paper, 2025). A progressive, neurodegenerative disease characterized by loss of function and death of nerve cells in several areas of the brain leading to loss of cognitive function such as memory and language. "Additionally, the orthologs of nhr-25(NR5A1 and NR5A2) and unc-62 (MEIS1, MEIS2, MEIS3) were linked to aging-related diseases such as dementia and Alzheimer’s disease." (PMID 40766245, 2025).
colon cancer (1 paper, 2020). "To further clarify the role of MEIS3 in cetuximab sensitivity, we analyzed 11 colon cancer cell lines in our lab; QPCR confirmed that SNU-61 had the lowest expression of MEIS3, while LOVO had the highest expression." (PMID 33376716, 2020). "In TCGA-COAD database, the expression of MEIS3 at the mRNA level was highly correlated with the overall survival rate of the colon cancer patients." (PMID 33376716, 2020).
diffuse large B-cell lymphoma (1 paper, 2020). "Meis1, Meis2, and Meis3 were upregulated in lymphoid neoplasm diffuse large B-cell lymphoma and thymoma cancers." (PMID 33402862, 2020). "MEIS3, which is the least studied isoform of the MEIS proteins, is highly expressed in breast-invasive carcinoma, diffuse large B-cell lymphoma, kidney renal papillary cell carcinoma, head, and neck SCC, and pancreatic adenocarcinoma, unlike other isoforms." (PMID 33402862, 2020).
hypertrophic cardiomyopathy (1 paper, 2025). A condition in which the myocardium is hypertrophied without an obvious cause. "In this study, we integrated bulk and single-cell transcriptomics with computational modeling to explore a potential link between the developmental transcription factor MEIS3 and the immunopathology of hypertrophic cardiomyopathy." (PMID 41200169, 2025).
leukemia (1 paper, 2022). A malignant (clonal) hematologic disorder, involving hematopoietic stem cells and characterized by the presence of primitive or atypical myeloid or lymphoid cells in the bone marrow and the blood. "We also observed the aberrant overexpression of MEIS1 and HOXA9, members of the same family as MEIS3, that is highly effective in transforming hematopoietic progenitors and driving mice toward a lethal leukemia." (PMID 36002858, 2022).
pancreatic adenocarcinoma (1 paper, 2020). "Meis2 and Meis3 expression were increased in pancreatic adenocarcinoma." (PMID 33402862, 2020).
prostate carcinoma (1 paper, 2020). A carcinoma that arises from epithelial cells of the prostate gland. "Several co-regulators which have been shown to interact with other HOX proteins are expressed in the 22Rv1 prostate cancer cells, including PBX1-3, MEIS1 and MEIS3, and PKNOX1." (PMID 32012197, 2020).
cancer (6 papers, 2017 to 2025). A tumor composed of atypical neoplastic, often pleomorphic cells that invade other tissues. "Given the importance of MEIS isoforms and cofactors in cancer biology, it is clear that the effects of MEIS3 on cancer biology need to be investigated." (PMID 33402862, 2020). "According to the GEPIA and BioGPS datasets, the expression of Meis1, Meis2, and Meis3 vary in different cancers." (PMID 33402862, 2020). "Moreover, recent pan-cancer analyses have revealed that MEIS3 and its family members influence the immune microenvironment." (PMID 41200169, 2025). "While cancer and cardiomyopathy are disparate diseases, these findings hint that MEIS3 might broadly act as an immunomodulatory switch in pathological states." (PMID 41200169, 2025). "Unfortunately, studies on the role of Meis3 in cancer biology are very limited." (PMID 33402862, 2020). "Next, for determining which member contributed to the generally impaired expression of MEIS subfamily in cancers, we investigated the expression of MEIS1, MEIS2, and MEIS3 in multiple TCGA cancers." (PMID 35351858, 2022). "CEBPB, MEIS3, and TEAD4 were co-expressed with has-miR-5p in cancers." (PMID 32637580, 2020).
tumor (3 papers, 2020 to 2025). "Furthermore, the downstream axis involving KDM3A/HOXA1/MEIS3 was proposed to be essential for miR-202-3p to facilitate its functionality as a tumor suppressor." (PMID 33520978, 2020). "Collectively, the experimental data demonstrated that miR-202-3p harbored tumor-suppressive properties during the development and progression of HCC through the KDM3A/HOXA1/MEIS3 axis in vitro and in vivo." (PMID 33520978, 2020). "Mouse tumor tissues were subject to qRT-PCR and Western blot analysis, and the results demonstrated that the miR-202-3p agomir diminished the protein expression of KDM3A, HOXA1, and MEIS3 in nude mice." (PMID 33520978, 2020).
MEIS3 also shares sentences with these, for which no sentence is quoted: breast carcinoma (2 papers); cardiac hypertrophy (1); cervical cancer (1); colorectal cancer (1); dementia (1); endometrial cancer (1); glioma (1); hepatocellular carcinoma (1); liver cancer (1); lung carcinoma (1); medulloblastoma (1); mesothelioma (1); pancreatic cancer (1); renal carcinoma (1); stomach cancer (1); thyroid cancer (1).